TXNRD3 (thioredoxin reductase 3)
Description:
Displays thioredoxin reductase, glutaredoxin and glutathione reductase activities. Catalyzes disulfide bond isomerization. Promotes disulfide bond formation between GPX4 and various sperm proteins and may play a role in sperm maturation by promoting formation of sperm structural components (By similarity).
Synonyms: TGR; TRXR3; TXNRD3IT1; TXNRD3NB; TR2; TR2IT1; TXNRD3NT1; TXNR3
Tractability: Small molecule: a high-quality ligand is known; it belongs to a druggable protein family. PROTAC: ubiquitination databases record sites on it; its protein half-life has been measured; a small molecule that binds it is known.
Target class: Enzyme; Oxidoreductase
Gene: Protein-coding gene on chromosome 3 (126,571,779 to 126,655,124, reverse strand). Ensembl gene ENSG00000197763.
Subcellular location: Cytoplasm; Nucleus; Microsome; Endoplasmic reticulum
Subcellular location (Human Protein Atlas): Nucleoplasm; Cytosol
Gene Ontology:
Molecular function: protein binding; thioredoxin-disulfide reductase (NADPH) activity; flavin adenine dinucleotide binding; oxidoreductase activity; oxidoreductase activity, acting on a sulfur group of donors, NAD(P) as acceptor
Biological process: cell redox homeostasis; spermatogenesis; cellular oxidant detoxification
Cellular component: cytosol; nucleoplasm; mitochondrion; cytoplasm; endoplasmic reticulum; nucleus
Genetic constraint (gnomAD): Loss-of-function variants: 41 observed, 50.59 expected, observed/expected ratio (o/e) 0.81, 90% interval 0.63 to 1.05. The upper end of that interval is the gene's LOEUF score, 1.05, which puts it in group 4 of 6, group 1 being the genes least tolerant of losing a copy. Missense variants: 518 observed, 571.05 expected, observed/expected ratio (o/e) 0.91, 90% interval 0.84 to 0.98. Synonymous variants: 188 observed, 203.21 expected, observed/expected ratio (o/e) 0.93, 90% interval 0.82 to 1.04.
Homologues: Orthologues: chimpanzee TXNRD3 (99% identical), macaque TXNRD3 (88% identical), dog TXNRD3 (86% identical), mouse Txnrd3 (84% identical), pig TXNRD3 (83% identical), rabbit TXNRD3 (82% identical), guinea pig TXNRD3 (80% identical), zebrafish txnrd3 (67% identical), tropical clawed frog txnrd3 (66% identical), rat Txnrd3 (60% identical), Caenorhabditis elegans F20D6.11 (15% identical), Drosophila melanogaster CG4199 (14% identical), and 1 more. Paralogues in human: TXNRD1 (65% identical), TXNRD2 (44% identical), GSR (28% identical), DLD (25% identical), AIFM3 (19% identical), AIFM1 (17% identical), PYROXD1 (14% identical).
Diseases named in the same sentence as TXNRD3 in open-access papers:
TXNRD3 is named in the same sentence as 24 diseases in open-access papers, as found by Europe PMC text mining. Sharing a sentence is not in itself a finding about the gene and the disease. The quoted sentences say what the papers report.
colon cancer (4 papers, 2012 to 2024). "TXNRD1, TXNRD3, SeP15, and SepX1 were associated with survival after colon cancer diagnosis; SeP15 and SepX1 remained significant after FDR multiple comparison adjustment (HRR 1.47, 95% CI 1.13,1.90 and HRR 1.47 95% CI 1.3,1.90 respectively)." (PMID 22615972, 2012). "TXNRD1, TXNRD2, TXNRD3, and SelN1 interacted with BMI to alter risk of colon cancer and TXNRD1 interacted with BMI to statistically alter risk associated with rectal cancer." (PMID 22615972, 2012). "Overexpression of Thioredoxin Reductase 3 (Txnrd3) may increase ROS production by inducing intracellular calcium efflux, followed by activation of the pyroptosis pathway, further inhibiting the growth and proliferation of colon cancer cells." (PMID 39011036, 2024). "Thioredoxin reductase 3 (Txnrd3) as selenoprotein was recently proved to cause intracellular calcium outflow and increase oxidative stress in colonic epithelial cell line, thereby activating the canonical GSDMD-dependent pyroptosis to inhibit the growth and proliferation of colon cancer cells." (PMID 36505474, 2022). "Two SNPs in TXNRD1 and four SNPs in TXNRD2 interacted with aspirin/NSAID to influence colon cancer; one SNP in TXNRD1, two SNPs in TXNRD2, and one SNP in TXNRD3 interacted with aspirin/NSAIDs to influence rectal cancer." (PMID 22615972, 2012).
breast carcinoma (2 papers, 2022 to 2024). "In the mFMC group, there was marked protein expression of BCL6, TXNRD3, CP and BIRC6, which have been linked with poor prognosis in human breast cancer." (PMID 38951817, 2024). "However, our study is the first to demonstrate higher levels of TXNRD3 in breast cancer and, in particular, in the TNBC subtype." (PMID 35158912, 2022). "Overall, considering both the CCLE and LINCS datasets, eight selenoproteins were overexpressed (DIO2, GPX1, GPX4, SELENOI, SELENON, SELENOS, TXNRD1 and TXNRD3) and five were down-expressed (DIO1, GPX2, GPX3, SELENOP and SELENOW) in TNBC compared to all other “non-TNBC” breast cancer subtypes." (PMID 35158912, 2022).
colorectal cancer (2 papers, 2012 to 2022). A primary or metastatic malignant neoplasm that affects the colon or rectum. "We evaluated the association between genetic variation in TXNRD1, TXNRD2, TXNRD3, C11orf31 (SelH), SelW, SelN1, SelS, SepX, and SeP15 with colorectal cancer risk." (PMID 22615972, 2012). "Higher TXNRD3 levels have been reported as indicative of advanced cancer stages in colorectal cancer." (PMID 35158912, 2022).
Obesity (2 papers, 2018 to 2022). Accumulation of substantial excess body fat. "Indeed, in a recent study of animal models, a combination of hyperglycemia, long-term insulin resistance and obesity was linked to reduced mRNA expression of thioredoxin reductase 3 (Txnrd3) along with selenoprotein Gpx3 and selenophosphate synthetase 2 (Sephs2) in adipose tissue." (PMID 35328380, 2022).
rectal cancer (2 papers, 2012 to 2019). A primary or metastatic malignant neoplasm that affects the rectum. "Two SNPs in TXNRD3 were associated with rectal cancer (rs11718498 dominant OR 1.42 95% CI 1.16,1.74 pACT 0.0036 and rs9637365 recessive 0.70 95% CI 0.55,0.90 pACT 0.0208)." (PMID 22615972, 2012). "In this paper we evaluate associations between genetic polymorphism in TXNRD1, TXNRD2, TXNRD3, C11orf31 (i.e. SelH), SelW, SelN1, SelS, SepX, and SeP15 and colon and rectal cancer." (PMID 22615972, 2012). "TXNRD2 (3 SNPs), TXNRD3 (3 SNPs), SelN1 (3 SNPs), and SepX1 (1 SNP) were associated with rectal cancer." (PMID 22615972, 2012). "Associations between TXNRD1, TXDRD2, TXNRD3, SelN1, and SepX1 and colon and rectal cancer." (PMID 22615972, 2012).
adenoma (1 paper, 2018). A neoplasm arising from the epithelium. "These included increasing down-regulation of GPX3, SELENOP, SELENOS, and SEPHS2 and up-regulation of GPX2, SELENOH, and TXNRD3, in groups of normal-matched tissues, adenomas, and adenomas with HGD." (PMID 30469315, 2018). "GPX2 and TXNRD3 showed a higher expression and GPX3, SELENOP, SELENOS, and SEPHS2 exhibited a lower expression in the disease tissue from adenomas and both cancer groups (p-values from 0.023 to <0.001)." (PMID 30469315, 2018).
diabetes (1 paper, 2022). "Only TXNRD3 was found to be associated with diabetes-related pathways according to the KEGG pathway identification, reaching a score of 5.5." (PMID 35328380, 2022). "Only TXNRD3 was found to be associated with diabetes-related pathways, reaching a score of 5.5 in machine learning-aided text mining." (PMID 35328380, 2022).
Epstein-Barr virus infection (1 paper, 2022). An infection that is caused by Epstein-Barr virus. "Finally, four significant KEGG enrichment pathways were identified (P < 0.05): beta-Alanine metabolism (SMOX, HIBCH), Pathways in cancer (GLI2, AR, TXNRD3, TRAF3, FGF16), Non-homologous end-joining (MRE11), Epstein-Barr virus infection (TRAF3, PSMD13, SIN3A)." (PMID 36330154, 2022). "Finally, the results of KEGG enrichment analysis showed four significantly enriched pathways (P < 0.05): beta-Alanine metabolism (SMOX, HIBCH), Pathways in cancer (GLI2, AR, TXNRD3, TRAF3, FGF16), Non-homologous end-joining (MRE11), Epstein-Barr virus infection (TRAF3, PSMD13, SIN3A)." (PMID 36330154, 2022).
germ cell tumor (1 paper, 2021). A benign or malignant, gonadal or extragonadal neoplasm that originates from germ cells. "In our study, we were limited by the number of samples of testicular germ cell tumors in the TCGA database, so we were unable to verify the expression level of TXNRD3 in testicular germ cell tumors." (PMID 33706760, 2021).
liver disease (1 paper, 2023). "When the liver is impaired in alcohol metabolism, gene expression in the liver (such as Txnrd1, Txnrd3, Txn1, and Txn2) decreases significantly, indicating the risk of liver disease and the need for timely intervention." (PMID 36765968, 2023).
melanoma (1 paper, 2016). A malignant, usually aggressive tumor composed of atypical, neoplastic melanocytes. "Particularly, murine melanoma cells increased the expression of TXNRD3 (thioredoxin reductase 3) during melanogenesis." (PMID 27206673, 2016).
selenium deficiency (1 paper, 2022). A nutritional deficiency disease resulting from inadequate selenium levels in the body, which can lead to impaired function of selenoproteins essential for antioxidant defense and thyroid hormone metabolism. "Consistently with other studies, the expressions of TXNRD2 and TXNRD3 were the highest in the selenium deficiency group." (PMID 35663374, 2022).
steatosis (1 paper, 2021). Increased lipid within the cytoplasm of cells. "Amongst the 13 genes, eight (DIO1, GPX2, SEPHS2, SELENOK, SELENOS, SELENOT, SELENOF, and SELENOW) had higher, and five (DIO3, GPX1, SELENON, SELENOO, and TXNRD3) had lower expression in steatosis." (PMID 34869521, 2021). "Besides the selenoproteins GPX2, DIO1, and SEPHS2, the gene for TRNAU1AP also had higher expression in steatosis in the “selenium metabolism and selenoproteins” pathway, and TXNRD3 had lower expression in steatosis." (PMID 34869521, 2021). "Of these genes, 11 coded for selenoproteins of which four genes had lower expression (SELENON, SELENOO, GPX1, and TXNRD3) and seven genes had higher expression (SELENOK, SELENOS, SELENOW, GPX2, GXP3, DIO1, and SEPHS2) in steatosis." (PMID 34869521, 2021). "Similarly, four out the five genes with lower expression in steatosis also had lower expression in NASH (SELENOO, SELENON, DIO3, and TXNRD3) compared to HC." (PMID 34869521, 2021).
cancer (8 papers, 2018 to 2025). A tumor composed of atypical neoplastic, often pleomorphic cells that invade other tissues. "TXNRD3 is involved in oxidative stress and has been associated with poor prognosis in various cancers." (PMID 38951817, 2024). "The specific physiological role of TXNRD2 and TXNRD3 in cancer cells remains to be determined, with some recent studies starting to enlighten their role separately." (PMID 36358931, 2022). "The expression levels of the TXNRD1 and TXNRD3 genes were mainly related to a poor cancer prognosis." (PMID 33706760, 2021). "Our study similarly found up-regulation in the TXNRD2 and TXNRD3 genes in various types of cancer, which was also correlated with a poor prognosis of immune-cell subtypes." (PMID 33706760, 2021). "The TXNRD1 and TXNRD3 genes are mainly related to poor prognoses, while other genes are related to good or poor prognoses depending on the type of cancer." (PMID 33706760, 2021). "These include key biological stress response genes like GPXs, TXNRD3, SELENOS, SELENOH, and the related SOD2 gene implicated in cancer cell survival, and genes such as SELENOP and SEPHS2 involved in Se biosynthesis." (PMID 30469315, 2018). "Our results demonstrate that exogenous SELENOV downregulated TXNRD1 and TXNRD3 mRNA expression, which may represent an important anticancer effect since both enzymes are frequent pharmacological targets in various cancer therapies." (PMID 41463386, 2025). "It is currently unclear the involvement of TXNRD2 and TXNRD3 in cancer." (PMID 36358931, 2022). "The role of TXNRD3 in cancer development is less known than the role of TXNRD2." (PMID 36358931, 2022). "Survival analysis revealed that the expression levels of these genes were closely related to patient survival, but the directions of the associations differed between different types of cancer, except for the TXNRD1 and TXNRD3 genes, which showed significant adverse prognoses in all cancer types." (PMID 33706760, 2021). "Whether TXNRD2 and TXNRD3 can serve as promising cancer treatment targets requires further analysis of how these genes play a role in oxidative stress in different cancers." (PMID 33706760, 2021). "But we did find that TXNRD3 lowly expressed in other types of cancer." (PMID 33706760, 2021). "This section will be focused on TXNRD1 as it has been the main TXNRD studied in cancer, and we will briefly comment on TXNRD2 and TXNRD3 and their relationship to cancer metabolism." (PMID 36358931, 2022). "TXNRD1 is a critical selenoprotein in cancer cells, and found to be overexpressed in several cancer types when compared to TXNRD2 and TXNRD3." (PMID 36358931, 2022). "Despite limited evidence, these findings intimate that TXNRD2 and TXNRD3 also inhibit oxidative stress via the thioredoxin system in cancers as TXNRD1, thereby promoting cancer cell resistance to cell death." (PMID 36358931, 2022). "Some genes were expressed at similar levels in different types of cancer, including GPX1, GPX4, TXNRD1, TXNRD2 and TXNRD3." (PMID 33706760, 2021). "In this study, changes in gene expression were observed for SELENOP, SELENOS, and TXNRD3 for all sample groups, while GPX4 was significant in the Irish cancers only and GPX1, SELENOH, and SELENON were differently regulated in the Czech CRCs." (PMID 30469315, 2018).
tumor (5 papers, 2018 to 2022). "Regarding the SELENOP level, TXNRD2 and TXNRD3 tumor tissue expression was negatively correlated (p = 0.037 and 0.045), while GPX1 had a higher expression in the normal tissue, p = 0.034." (PMID 30469315, 2018).
TXNRD3 also shares sentences with these, for which no sentence is quoted: schistosomiasis (4 papers); Arthritis (1); colorectal tumor (1); glioblastoma (1); Hyperglycemia (1); Insulin resistance (1); leishmaniasis (1); neurological diseases (1); triple-negative breast carcinoma (1).